ENSG00000289346 (Novel protein)
Gene: Protein-coding gene on chromosome 7 (74,796,150 to 74,890,585, reverse strand). Ensembl gene ENSG00000289346.
Genetic constraint (gnomAD): Loss-of-function variants: 4 observed, 10.51 expected, observed/expected ratio (o/e) 0.38, 90% interval 0.19 to 0.87. The synonymous counts are far from expectation, so gnomAD's model fits this gene poorly and the ratio says little. Missense variants: 51 observed, 165.33 expected, observed/expected ratio (o/e) 0.31, 90% interval 0.25 to 0.39. Synonymous variants: 18 observed, 64.83 expected, observed/expected ratio (o/e) 0.28, 90% interval 0.19 to 0.41.